MTOR (mechanistic target of rapamycin kinase)
Diseases named in the same sentence as MTOR in open-access papers (continued):
Sharing a sentence is not in itself a finding about the gene and the disease.
allergic asthma (continued). "In conclusion, while our earlier studies demonstrate that mTOR signaling plays an important role during the early phases of allergic asthma, the studies we report here suggest that its role is more limited during allergen re-exposure and chronic/established disease." (PMID 23349887, 2013). "As supporting evidence for the current study, it has been suggested that inhibition of mTOR with rapamycin has widely immunosuppressive activities at their disposal to attenuate AHR and airway inflammation in experimental allergic asthma." (PMID 29234390, 2017). "Given that the PI3K-AKT-mTOR signaling pathway lies in the intersection of allergic asthma and cataract, we analyzed the effector molecules of these pathways, including p44/p42 MAPK, p-p44/p42 MAPK, Akt, p-Akt Ser473, p-Akt Thr308, mTOR, and p-mTOR, after VPA treatment." (PMID 37686250, 2023). "The goal of our study was to determine whether mTOR inhibition with rapamycin would suppress the key features and mediators of HDM-induced allergic asthma in established asthmatic disease." (PMID 23349887, 2013).
Allergy (16 papers, 2013 to 2025). An allergy is an immune response or reaction to substances that are usually not harmful. "Thus, hyperactivity of mTOR in the intestinal tract might lead to a loss of immune regulation and barrier integrity, leading to an inflammatory profile possibly associated with allergy." (PMID 31057483, 2019). "Inhibition of mTOR signaling by a combination of the AAs His, Lys and Thr in this mast cell model was accompanied by an inhibition of acute mast cell degranulation and an attenuated allergy-associated cytokine production following antigen-IgE mediated activation." (PMID 31057483, 2019). "The Th1/Th2 cell balance is a major factor in the induction of allergic diseases, and T cells rely on mammalian target of rapamycin (mTOR) signaling to maintain immune and metabolic signals in appropriate states." (PMID 35889810, 2022). "Another link between metabolism and the regulatory role of DCs in allergy has been confirmed by using rapamycin (mTOR inhibitor) and murine models of mTOR gene depletion." (PMID 34394086, 2021). "In contrast, increasing the activity of PI3K/AKT/mTOR pathway in MS and DM is a therapeutic approach that is opposed to cancer and allergies." (PMID 31030467, 2019). "The balance of Tfh and Th1 cell differentiation in vivo is regulated by IL-2 signaling through PI3K, AKT and mTOR, and both mTORC1 and mTORC2 essentially promote Tfh cell differentiation and germinal centers (GC) formation, which cannot be ignored in allergic diseases." (PMID 36964157, 2023). "Furthermore, we want to confirm the potential of SBP as a major anti-allergy therapeutic agent through Th1/Th2 cell balance by regulating the activity of the PI3K/mTOR mechanism." (PMID 35889810, 2022). "SBP suppressed the gene expression of the PI3K/mTOR mechanism of action that regulates T cell differentiation and growth and inflammatory response, thereby restoring the Th1/Th2 cell balance from the allergy state to the normal state and improving the biomarker of allergic symptoms." (PMID 35889810, 2022). "Pathways related to intracellular signalling pathway, stress response, VEGF and MTOR related, the latter showed in the last years to be related with allergy; and oxidative phosphorylation are up-regulated, like FOXP1, SERPIN family, SOD2, caspase family, PGF, CYB5B, SERP1 and SLC25A4." (PMID 34784380, 2021). "Our work indicates that mTOR-VEGF pathway is hyperactivated in SXNI induced pseudo-allergic reactions, and rapamycin might be a potentially drug to prevent SXNI mediated pseudo-allergic reactions." (PMID 32615844, 2020). "Thus, the increase in PI3K/AKT/mTOR signaling activity is due to the creation of a series of cytokines in the immune system of Th2 cells in cancers and allergies." (PMID 31030467, 2019). "However, by using these mTOR specific knockout mice, we discovered more aggressive eosinophil development, resulting in elevated levels of eosinophil infiltration in allergies." (PMID 29720621, 2018). "Interestingly, the mTOR pathway plays an important role in macrophage polarization during infection, regulating type 2 immunity, inflammation and allergy." (PMID 27043018, 2016). "Additionally, SBP extract treatment inhibited phosphatidylinositol-3-kinase/mammalian target of rapamycin (PI3K/mTOR) signaling activity to further inhibit degranulation and allergy mediator generation and control the balance of Th1/Th2 cells, which can induce an allergic reaction when disrupted." (PMID 35889810, 2022). "Although these studies demonstrated an important role for the mTOR pathway during early allergic sensitization and asthmatic disease processes, it was unclear whether mTOR signaling would be important during allergen re-exposure or during established/progressive allergic disease." (PMID 23349887, 2013). "Since mTOR activation seems to be an effect common to several forms of ASD, including the allergy mechanism discussed in the current review, it might be useful to prevent or to inhibit the activation of mTOR." (PMID 29232822, 2017).
Allergy (continued). "Indeed, mTOR inhibition attenuated OVA-mRNA-LNP–induced CD8+ T cells in the lung and the CD38+KLRG1– CD8+ T cell subset, including perforin production, while preserving the anti-allergy effect of the vaccination." (PMID 40985871, 2025).
autosomal dominant polycystic kidney disease (16 papers, 2007 to 2025). Autosomal dominant form of polycystic kidney disease. "Additionally, periostin/αv/ILK (integrin-linked kinase) and periostin/αvβ3/AKT/mTOR signaling pathways both aggravated the growth of cyst epithelial cells in autosomal dominant polycystic kidney disease (ADPKD)." (PMID 36611844, 2022). "mTOR also plays an important role in mediating cyst formation and enlargement in autosomal dominant polycystic kidney disease." (PMID 32295297, 2020). "Inhibition of mTOR by rapamycin or one of its analogues represents a potentially novel treatment for autosomal dominant polycystic kidney disease." (PMID 32295297, 2020). "have demonstrated that Saikosaponin-d, a sarcoplasmic/endoplasmic reticulum Ca2+ ATPase pump (SERCA) inhibitor, inhibits proliferation by up-regulating autophagy via the CaMKKβ/AMPK/mTOR pathway in ADPKD (autosomal dominant polycystic kidney disease) cells." (PMID 30470173, 2018). "In autosomal dominant polycystic kidney disease, mTOR is constitutively hyperactivated, leading to inappropriate proliferation and the formation of thousands of cysts within the kidneys." (PMID 24379984, 2013). "The clinical efficacy of mTOR inhibitors for autosomal dominant polycystic kidney disease is still under investigation with several ongoing clinical trials." (PMID 24379984, 2013). "In human patients with autosomal dominant polycystic kidney disease, there is evidence of mTOR hyperactivation in renal cells lining the cysts, and rapamycin has been shown to delay progression in mouse models of the disease." (PMID 24379984, 2013). "This single center, randomised controlled, open label trial assesses the therapeutic effect, safety and tolerability of the mTOR inhibitor sirolimus (Rapamune®) in patients with autosomal dominant polycystic kidney disease and preserved renal function." (PMID 17868472, 2007). "Evidence from one of the most common ciliopathies, autosomal dominant polycystic kidney disease (ADPKD), shows that ciliary cAMP drives renal cell proliferation and cyst formation by activation of mTOR, a protein with oncogenic potential." (PMID 40301543, 2025). "In fact, SGLT2 inhibitors are expected and being studied whether to ameliorate Alzheimer’s disease and autosomal dominant polycystic kidney disease (ADPKD) via improving their autophagy deficiencies, in which diseases the AMPK/mTOR pathway influences their progression." (PMID 34744742, 2021). "We confirmed elevated mTOR signaling in cysts of kidneys from patients with end-stage autosomal dominant polycystic kidney disease (ES-ADPKD) relative to normal kidneys (NHK) from unaffected individuals." (PMID 20169078, 2010). "Analysis from a two-year randomized controlled trial, CRAD001ADE12, suggests that the accelerated growth of cysts in patients with autosomal dominant polycystic kidney disease (ADPKD) can be slowed down with the use of everolimus, a mammalian target of rapamycin (mTOR) inhibitor." (PMID 39568720, 2024).
brain injury (16 papers, 2015 to 2025). Acute and chronic (see also brain INJURIES, CHRONIC) injuries to the brain, including the cerebral hemispheres, CEREBELLUM, and brain STEM. "The AMPK/mTOR pathway plays an important role in sensing the stress responses following brain injury." (PMID 39744433, 2025). "We investigated the effect of triolein on the AKT/mTOR signaling pathway after IS-induced brain injury." (PMID 39639187, 2024). "Overall, these results indicate the involvement of the AKT/mTOR signaling pathway in the crucial function of triolein in exerting anti-inflammatory effects and inhibitory effects on autophagy in IS-induced brain injury." (PMID 39639187, 2024). "The ability to regenerate after ischemic brain injury is closely related to the enhancement of mTOR/p-S6 activity, which increases the expression of growth associated protein-43 (GAP-43)." (PMID 37426810, 2023). "Although some studies have suggested that the activity of mTOR is detrimental, there is evidence that upregulation of Akt/mTOR activity is neuroprotective against ischemic brain injury, which is in accordance with our previous studies." (PMID 34900085, 2021). "A previous study indicated that DEX exerts an anti-inflammatory effect via the activation of PI3K/Akt/mTOR signaling in rats with traumatic brain injury." (PMID 31351473, 2019). "Previous studies have shown that AKT/mTOR activation can reduce IS-induced brain injury." (PMID 39639187, 2024). "In summary, our data showed that exposure to 2% sevoflurane for 3 h induces abnormal morphological proportions, but not density, of dendritic spines by impacting the phosphorylation of PI3K/AKT/mTOR pathway, which may be effect on developmental brain injury." (PMID 36248658, 2022). "Recent studies demonstrated that mammalian target of rapamycin (mTOR) inhibitors (rapamycin) might have antiepileptogenic effects in the controlled cortical impact model of traumatic brain injury." (PMID 31798512, 2019). "In neonatal cerebral hypoxic-ischemic brain injury, notoginsenoside R1 was demonstrated to inhibit neuronal apoptosis and promote cell survival via the PI3K-Akt-mTOR/JNK signaling pathway." (PMID 30891181, 2019). "Together, our findings suggested that neuronal and endothelial IRS-1 had opposite effects on the neurovascular integrity and damage after neonatal HI brain injury and that endothelial IRS-1 worsens neurovascular integrity after HI via mTOR-mediated tight junction protein disassembly." (PMID 34226528, 2021). "In this study, we revealed that controlled reoxygenation treatment could reduce neuron and glial cell apoptosis caused by hypoxia and exert an anti-inflammation effect on hypoxia-induced brain injury mice by downregulating JAK2/STAT3 and AMPK/mTOR signaling pathway." (PMID 31719034, 2019).
chronic lymphocytic leukemia (16 papers, 2012 to 2025). "In chronic lymphocytic leukemia patients, the inhibition of mTOR can enhance AKT signaling, which can be overcome by dual PI3K/mTOR inhibitors." (PMID 36986560, 2023). "A histone deacetylase inhibitor (HDACi) MGCD0103 has been shown to inhibit autophagy by functionalizing PI3K/AKT/mTOR pathway as well as caspases in B-cell chronic lymphocytic leukemia cells (CLL)." (PMID 25402829, 2014). "RBMX regulates the mTOR signaling pathway by stabilizing CPT1A and participates in lipid metabolism and proliferation in chronic lymphocytic leukemia, promoting the progression of the disease." (PMID 40941025, 2025). "Specifically, two studies investigated the efficacy of idelalisib, a PI3K-δ isoform inhibitor, approved for chronic lymphocytic leukaemia (CLL), and that of the dual, pan PI3K/mTOR inhibitor NVP-BEZ235." (PMID 34638901, 2021).
cutaneous melanoma (16 papers, 2013 to 2025). A primary melanoma arising from atypical melanocytes in the skin. "Our results are in line with previous data in NRAS-mutated skin melanoma cell lines where Omipalisib was the most potent inhibitor of the PI3K/mTOR pathway." (PMID 35326726, 2022). "We have previously reported differential activation of the MAPK and AKT/mTOR signalling pathways in uveal and skin melanomas harbouring, respectively, GNAQ and BRAF mutations." (PMID 23904987, 2013). "DIOS treatment led to decreased phosphorylation of PI3K, Akt, and mTOR in cutaneous melanoma cells, and immunohistochemistry revealed significantly higher p-Akt expression in the control group of tumor-bearing mice." (PMID 39844566, 2025). "Activation of the mTOR pathway is thought to be closely related to the pathogenesis of cutaneous melanoma, while AMPK activation inhibits mTOR and its effectors, thereby reducing energy consumption." (PMID 34471465, 2021). "With the clinical availability of PI3K, AKT and mTOR inhibitors, a number of trials are now ongoing in cutaneous melanoma." (PMID 28938534, 2017). "Evidence has been obtained that skin melanoma cells display greater UV-induced mitochondrial oxidative stress under mTOR inactivation, implying mTOR promotes glycolysis for the maintenance of energy and redox homeostasis." (PMID 28250388, 2014). "In a previous report we described MAPK and AKT/mTOR pathway activations in a series of skin melanomas, where an association between BRAF mutation and high mTOR pathway activation was observed." (PMID 23904987, 2013). "Notably, dysfunction mutations of NF1 induce BRAF inhibitor resistance by activating RAS and its downstreams including both MAPK and PI3K/AKT/mTOR pathways in cutaneous melanoma." (PMID 32333246, 2020). "Furthermore, GSEA analysis of transcriptome data highlighted significant enrichment of the PI3K/Akt pathway, supporting the conclusion that DIOS promotes apoptosis and autophagy through the inhibition of the PI3K/Akt/mTOR signaling pathway in cutaneous melanoma." (PMID 39844566, 2025). "Furthermore, the study suggested that DIOS could induce apoptosis and autophagy by restraining the PI3K/Akt/mTOR signaling pathway in cutaneous melanoma." (PMID 39844566, 2025). "EGFR also has potential as an important therapeutic target in human cancer because it may be involved in the progression of cutaneous melanomas specifically and more generally acts upstream of mTOR as a signal transducer of mitogens, which play a role in cancer pathogenesis and development." (PMID 36077992, 2022). "On the other hand, we speculate that AKT-mediated PGC-1α inhibition and the subsequent inactivation of metabolic gene transcription are more effectively exerted by skin melanoma cells to counteract mTOR-inhibited PGC-1α degradation upon UA-induced IGF-1 receptor signaling." (PMID 28250388, 2014). "The UA-induced NF-κB activation in skin melanoma cells was relatively sustained in response to mTOR inhibition, suggesting that both AKT and the AKT-activated mTOR exert regulatory effects on PGC-1α expression." (PMID 28250388, 2014). "We also tested the effects of the FASN and mTOR inhibitors on a non-GNAQ mutant cutaneous melanoma cell line, A375." (PMID 37444561, 2023). "Similarities in genetic signatures of mucosal and skin MM suggest similar mechanism of development; however, unlike skin melanoma, there is less BRAF mutation and more of PI3K/AKT/mTOR pathway alterations in mucosal MM." (PMID 36407184, 2022). "The antagonistic effects of AKT and mTOR provide a potential explanation for the up-regulated transcription of metabolic enzymes observed in RPE cells but not in skin melanoma cells." (PMID 28250388, 2014).
invasive breast carcinoma (16 papers, 2005 to 2025). A carcinoma that infiltrates the breast parenchyma. "HER2 overexpression in invasive breast cancer has been linked to increased metabolic activity, including upregulation of the mTOR pathway and increased glycolysis." (PMID 40119362, 2025). "COL17A1 inhibits cancer cell migration and invasion by inactivating AKT/mTOR pathway, and its over-expression is linked with longer survival in patients with invasive breast cancer." (PMID 36936416, 2023). "cBioPortal downloaded from TCGA datasets of 1084 invasive breast carcinoma patient samples estimated a positive correlation of mRNA expression of mTOR with GPR141 mRNA expression level (Spearman’s correlation = 0.210, P = 2.70e-12)." (PMID 37204251, 2023). "This can include women with invasive breast cancer who are receiving an mTOR inhibitor as a component of their treatment regimen." (PMID 27334013, 2016). "We used the starBase v3.0 project, which contained the gene expression profiles of 1104 TCGA invasive breast carcinomas, to determine the association between CUL1 with mTOR, and revealed a strong positive correlation between CUL1 and mTOR expression levels (r = 0.195, P = 6.90e-11)." (PMID 37204251, 2023). "Gene Set Enrichment Analysis (GSEA) of the Cancer Genome Atlas (TCGA) Breast invasive carcinoma (BRCA) dataset indicated that low expression of SALL2 correlates with a PI3K/Akt/mTOR signaling signature, suggesting that loss of SALL2 might activate PI3K/Akt/mTOR pathway." (PMID 31657150, 2019). "We performed immunostaining for mTOR, phosphorylated (p)-mTOR, p-AKT, and p-p70S6K in tumor tissue from 590 women (464 African Americans/Blacks and 126 Whites) with newly diagnosed invasive breast cancer in the Women’s Circle of Health Study." (PMID 33024820, 2020). "One study on Eph receptors and invasive breast carcinoma suggested that the level of FKBP1A was significantly affected by EphB6, which was a target mRNA of miR-100, the changes in miRNAs and the target mRNA may have a role in PI3K/Akt/mTOR pathways." (PMID 32497068, 2020). "In contrast, a study by Ma and colleagues found that, despite the activation of mTOR and its downstream signaling components, including 4E‐BP1 and S6K1 in invasive breast cancer, these markers did not exhibit a statistically significant correlation with prognosis." (PMID 39448637, 2024).